HLA-B (major histocompatibility complex, class I, B)
Diseases named in the same sentence as HLA-B in open-access papers (continued):
Sharing a sentence is not in itself a finding about the gene and the disease.
Stevens-Johnson syndrome (45 papers, 2007 to 2026). Stevens-Johnson syndrome is a limited form of toxic epidermal necrolysis characterized by destruction and detachment of the skin epithelium and mucous membranes involving less than 10% of the body surface area. "In particular, the HLA-B*15:02 allele is highly correlated with Stevens-Johnson syndrome/toxic epidermal neurolysis (SJS/TEN) triggered by carbamazepine, oxcarbazepine, and phenytoin in some Asian populations, including Chinese, but not other SCARs." (PMID 39188942, 2024). "Just as the association of HLA-B*1502 and Stevens-Johnson syndrome was mainly found in Southeast Asian populations." (PMID 38075685, 2023). "For example, to prevent life-threatening Stevens-Johnson syndrome among some Asians, HLA-B*1502 allele genotyping prior to the initiation of carbamazepine therapy in new patients of Asian ancestry is now considered the standard of care." (PMID 36980961, 2023). "Further progress has been made on the issue regarding ancestry; for example, there is now extensive evidence of the association between the HLA-B-1502* variant and carbamazepine-induced Stevens-Johnson syndrome in individuals of East Asian descent." (PMID 34615849, 2021). "In fact, has been well reported that Asian patients HLA-B 1502 positive are at a higher risk for Stevens-Johnson syndrome during the treatment with carbamazepine." (PMID 21629443, 2010). "After having demonstrated the high association of Stevens-Johnson syndrome to HLA-B*1502 in Han Chinese, they eluted the peptides from HLA-B*1502-positive cell lines incubated with carbamazepine." (PMID 23282405, 2008). "One example was the association of HLA-B*1502 and the development of Stevens-Johnson syndrome/toxic epidermal necrolysis in Taiwanese and Southeast Asian populations that led physicians to perform a genetic test before prescribing aromatic ASMs to these ethnic groups to prevent severe skin ADR." (PMID 38075685, 2023). "So far, the evidence for a clinical PGx effect on ADRs is probably best for non-dose-related hypersensitivity reactions, such as carbamazepine induced Stevens-Johnson syndrome in the carriers of the HLA-B*1502 allele, or abacavir-related hypersensitivity in the carriers of the HLA-B*5701 allele." (PMID 32527038, 2020). "So far, 515 patients have been genotyped for HLA-B*1502 which is associated with risk of developing Stevens-Johnson syndrome following use of carbamazepine, in addition to 318 patients genotyped for TPMT in patients that may be treated with thiopurines." (PMID 24723935, 2014). "HLA-B*15:02 screening before carbamazepine (CBZ) prescription in Asian populations is the recommended practice to prevent CBZ-induced Stevens-Johnson syndrome (CBZ-SJS)." (PMID 28358139, 2017). "The HLA-B*1502 allele was not identified in other races or ethnicities, but recent data identified similar HLA antigens, HLA-B*1511 and HLA-A3101, in Stevens-Johnson syndrome and severe cutaneous reactions in a Korean population." (PMID 26105627, 2015). "The associations between abacavir hypersensitivity and HLA-B*57:01 and carbamazepine-induced Stevens-Johnson syndrome and HLA-B*15:02 have been implemented in clinical practice." (PMID 26254050, 2015). "However, human leukocyte antigen (HLA)-A and HLA-B testing before use of carbamazepine and oxcarbazepine is currently recommended to avoid serious side effects (e.g. Stevens-Johnson syndrome) (International Society of Psychiatric Genetics (ISPG) 2019)." (PMID 41408787, 2026). "Likewise, screening for HLA-B*15:02 in Taiwanese patients reduced the incidence of carbamazepine-induced Steven Johnson’s syndrome to 3.3 cases per 1000 from 25 per 1000." (PMID 39941601, 2025). "A strong association was found in people with epilepsy and Han Chinese origin between a genetic marker, HLA-B*15:02, and Stevens-Johnson syndrome induced by treatment with carbamazepine, probably due the role of this allele in mediating the activation of cytotoxic T-lymphocytes." (PMID 28082152, 2018).
viral infections (41 papers, 2011 to 2025). "Human leukocyte antigen (HLA)-B*35 is considered a predisposing factor, and viral infection is believed to be a trigger." (PMID 41488629, 2025). "On the other hand, in the group of late onset T1D subjects, the significantly more frequent HLA alleles were HLA-B*27 alleles, HLA-C*01:02:01 and C*02:02:02, all known to be associated with increased protection against viral infections." (PMID 39185409, 2024). "HLA-B*57:01 is an HLA allelic variant associated with positive outcomes during viral infections through interactions with T cells and NK cells, but severe disease in persons treated with the anti-HIV-1 drug abacavir." (PMID 35632760, 2022). "The HLA-Bw4 allele HLA-B*B57:01 can be advantageous in the control of viral disease, as evidenced in detail for HIV-1, but is detrimental for persons receiving abacavir." (PMID 35632760, 2022). "This is a relevant observation for an HLA-B allele which predisposes to Spondyloarthritis, particularly to AS, but which is also protective in several viral infections." (PMID 31212633, 2019). "Moreover, subjects with late-onset had a higher frequency of alleles HLA-B*27 (p-value=0.003), HLA-C*01:02:01 (p-value=0.027) and C*02:02:02 (p-value=0.01), known to be associated with increased protection against viral infections." (PMID 39185409, 2024). "The HLA-B*27:05 allele plays an important role in long-term protection against viral infection." (PMID 39201523, 2024). "The influence of the HLA-B –21 M/T dimorphism has also been investigated in the context of other viral infections, such as HIV." (PMID 40650195, 2025). "For example, if the individual possesses rare HLA-A allotype but dominant HLA-B or C allotypes, the HLA-B or HLA-C restricted epitopes also can elicit robust T-cell immunity to defend against viral infection." (PMID 40469303, 2025). "Similar to previous conditions, the HLA-B*27:05-bound peptide pools were isolated from either uninfected or VACV-infected cells treated with acid stripping after virus infection." (PMID 34638844, 2021). "Complexes of HLA-B*27:05-bound peptide pools were isolated from vaccinia virus (VACV)-infected cells treated with acid stripping after virus infection." (PMID 34638844, 2021). "KIR3DL1 is a protein coding gene and is a inhibitory receptor that binds to groups of HLA-A and HLA-B allotypes, which plays an important role in viral infections, cancers, autoimmunity, and transplantation." (PMID 34738870, 2021). "It is reported that the CD8+ T cell-mediated HLA allele (HLA-B*5801, PDB ID 5IM7) unique interaction with immune dominant peptide contributes as a potential to control and prevent viral infection." (PMID 33828922, 2021). "Cross-reactive T cells were also found during a phase of mutant virus infection in patient KI-705 and in 23 of 24 HLA-B*35:01+ individuals infected with the mutant virus." (PMID 34523962, 2021). "In this context, it is also important to take into consideration that the expression of HLA-B can be modified only marginally during certain viral infections." (PMID 28603523, 2017). "In particular, an important combined role for KIR3DS1 and HLA-B Bw4-I80 in controlling viral infections and a higher protection against leukemic relapses in donor equipped with activating KIRs in haplo-HSCT has been described." (PMID 28603523, 2017). "Our results and previous results indicate that HLA-A*30, HLA-B*13*, and A*30 -B*13* haplotypes play important roles in the outcome of viral infection." (PMID 27760141, 2016). "With frequencies ranging from 0.2–0.6% of the CD8+ T cells, and 1–8% of the activated CD38+, CD8+ T cells, all yellow fever vaccinated HLA-B*57:01 positive donors (n = 6) recognized this wild type K9F epitope." (PMID 25674793, 2015).
viral infections (continued). "Thus, the CD8+ memory T cells induced after yellow fever vaccination include subsets of T-cells with specificities that cross-recognize several different structurally related, variant peptides, which can only be presented by HLA-B*57:01 in the presence of abacavir." (PMID 25674793, 2015). "Kaplan Meier analysis revealed significantly increased mortality in HLA-B*57-positive patients with HIV-infection (p=0.032) and HIV/HCV-co-infection (p=0.004), which was apparently linked to non-viral infections." (PMID 26241854, 2015). "A panel of yellow fever virus vaccinees, were used to identify a dominant HLA-B*57:01-restricted, yellow fever-specific CD8+ T cell epitope, K9F (KTWGKNLVF)." (PMID 25674793, 2015). "Multiple sclerosis, an auto-immune disease that has been controversially reported as being possibly triggered by viral infections, is positively associated with HLA-A*02, C*08, DRB1*15, DQA1*01, and DQB1*06, whereas HLA-B*44 is reported to be protective." (PMID 21829673, 2011). "Induction of HLA-B could be evaluated in response to the high HERV-K levels in PAH monocytes as HLA-B is increased in response to viral infections." (PMID 40234964, 2025). "The HLA-B*08:01 allele has many immune functions, including viral load regulation, while the HLA-B*13:02 allele is also involved in viral development, having the role of controlling the HIV viral infection." (PMID 39201523, 2024). "As IFN‐α and IFN‐γ increase the transcription of HLA‐B among other MHC class I loci during acute viral infection, a particularly strong HLA‐B response could boost the cytotoxic immune response and mitigate acute‐phase symptoms." (PMID 30150281, 2018). "The amino acid at position 156 in HLA-B is not in the peptide-binding grove, but this particular amino acid position has previously been shown to be associated with persistent viral infection." (PMID 28806749, 2017). "The specific mechanisms of HLA-B*13 in different viral infections need to be further studied." (PMID 27760141, 2016). "Guillain-Barré syndrome is of unknown etiology but has been reported after viral infections including WNV; and the syndrome is associated with HLA-B*44, Cw*01, DRB1*0803 and DRB1*13." (PMID 21829673, 2011). "Also, HLA-B*27:05 in complex with other peptides leads to incapacity of KIR3DL1 to recognize this allele, and the result is increased activation of NK cells during viral infection." (PMID 39201523, 2024). "There might also be a bias towards HLA-B-restricted epitopes in other viral infections, likely due to the fact that HLA-B alleles are the most polymorphic HLA class I alleles; however, the almost exclusive restriction of HDV epitopes by HLA-B alleles could also point towards a functional relevance." (PMID 35215790, 2022). "Three types of HLA-B*35:01-restricted T cells specific for YF9/FF9 were elicited during the clinical course, starting from a phase of wild-type virus infection to that dominated by mutant virus." (PMID 34523962, 2021). "The CXCL10/11high basal cells also had upregulated mRNA encoding for complement components (C1R and C1S), MHC class I (HLA-A, HLA-B, HLA-C, and B2M), and metalloproteases MMP2 and MMP13, the latter reducing repair during viral infection in bronchial epithelial cells." (PMID 40980495, 2025). "Whether these allotypic combinations are similarly protective against other viral infections such as human papilloma virus (HPV) and Epstein-Barr virus (EBV) which, like HIV, induce downregulation of HLA-B, remains to be determined." (PMID 24919192, 2014). "Moreover, the presence of Trp at position 156 in HLA-B*35:62 was shown to confer a TAP-independent mode of peptide loading that could be suggestive of conferring the ability of peptide presentation via non-classical pathways and its potential role in immune response against viral infections." (PMID 26758079, 2016).
melanoma (39 papers, 2006 to 2025). A malignant, usually aggressive tumor composed of atypical, neoplastic melanocytes. "Our dataset included 26 of the 27 HLA-B alleles for which expression levels had been determined previously in the tapasin-deficient melanoma cell line M553 using W6/32 for cell surface staining of transfected cells." (PMID 33097667, 2020). "The alleles that differed among melanoma patients were HLA-A*03, HLA-B*037, *53, *54, *58, *59, *78, HLA-DRB1*1102, HLA-DQB1*0201, and *0302 with corresponding P values .042.033.050.046.001.021.004.021.006 and .033, respectively." (PMID 20549830, 2010). "Consequently, the HLA-A and HLA-B expressions in the melanoma cell lines might be more susceptible to UVB irradiation than in PHMs." (PMID 40243413, 2025). "In fact, we found that ANGPTL2 mRNA levels were positively correlated with those of HLA‐A, HLA‐B, and HLA‐C in melanoma patients, suggesting that in this cancer context ANGPTL2 signaling does not regulate MHC‐I expression." (PMID 37452654, 2023). "HLA-B, C heavy chains were detected only in the cytoplasm of melanoma cells in both pre- and post-treatment biopsies." (PMID 33407577, 2021). "Both HLA-A and HLA-B, C heavy chains had a low expression both in terms of percentage of stained melanoma cells and of staining intensity." (PMID 33407577, 2021). "In the present study, we developed a prognostic and diagnostic biomarker with 5 selected MRGs (A2M, DUSP6, HLA-B, SERPINE2, and SLC26A2), all of which acted as risk factors in melanoma." (PMID 33324561, 2020). "Higher TAP1 (a), HLA-A (b), HLA-B (c) and HLA-C (d) mRNA transcript levels correlated with an increased OS of melanoma patients." (PMID 32825219, 2020). "Among the HLA-specific mAbs tested, only the HLA-B,C-specific mAb B1.23.2 was able to shift melanoma cells from Warburg metabolism to a more Oxphos." (PMID 31454998, 2019). "This study shows for the first time that the HLA-B,C-specific mAb B1.23.2 is able to reprogram the glycolysis addiction of melanoma cells." (PMID 31454998, 2019). "In this study we have screened HLA-specific mAbs for their effects on the metabolic activity of cultured human melanoma cells and we have found for the first time that the HLA-B,C-specific mAb B1.23.2 inhibits glycolysis." (PMID 31454998, 2019). "On the whole, the described results suggest that HLA class I antigens, and in particular the gene products of HLA-B and C loci play a role in the motility of melanoma cells by regulating their metabolism." (PMID 31454998, 2019). "Analysis of monocarboxylate transporters showed an increased level of MCT1 (promoter of lactate influx) associated with an unchanged level of MCT4 (promoter of lactate efflux) in HLA-B,C-specific mAb B1.23.2 -treated melanoma cells." (PMID 31454998, 2019). "Overall, these results suggest that among the HLA-specific mAbs tested, only the HLA-B,C-specific mAb B1.23.2 inhibits glycolysis and glutamine metabolism, possibly reconverting melanoma cells to a more Oxphos metabolism." (PMID 31454998, 2019). "We examined the HLA-B*07:02-NY-ESO-1 restricted CD8+ T-cell repertoire, previously shown to exhibit a diverse TRBV gene repertoire in vaccinated HLA-B*07:02+ melanoma patients." (PMID 29531227, 2018). "Co-expression of other inhibitory HLA-A and/or HLA-B with homozygous HLA-C group was similar among melanoma patients and healthy donors." (PMID 23483943, 2013). "HLA-A and -B carrier frequencies of stage IV melanoma patients (739 HLA-A; 709 HLA-B) and healthy bone marrow donors were compared using a two sided chi-square test with a 95% confidence interval and sorted according to the absolute difference." (PMID 16533402, 2006). "Although we could show the same effect in two unrelated cell lines, a lymphoma (Raji) and a melanoma cell line (Mel JuSo), larger studies need to be conducted to show a general effect with the many different HLA-B allomorphs known to date." (PMID 35087068, 2022).
melanoma (continued). "Melanoma patients’ sera contain IgG antibodies against HLA-E as well as HLA-B and HLA-C." (PMID 35323192, 2022). "Furthermore, a recent study indicated that besides playing a role in the immune response, HLA class I antigens, and in particular HLA-B and C, are crucial in the metabolism of melanoma cells, sustaining glycolysis." (PMID 33920048, 2021). "Therefore, we analyzed the Phalloidin and Paxillin phosphorylation staining in A375-M6 and FO-1β2 melanoma cells following a 24 h incubation with the HLA-B,C-specific mAb B1.23.2." (PMID 31454998, 2019). "Moreover, the expression of microphthalmia-associated transcription factor (MITF), a well-known PGC-1α transactivator in melanoma cells, was upregulated in cells incubated with HLA-B,C-specific mAb B1.23.2." (PMID 31454998, 2019). "Additionally, the expression level of PDP2 was upregulated without any detectable change in the expression of PDK1 in FO-1β2 melanoma cells incubated with the HLA-B,C-specific mAb B1.23.2." (PMID 31454998, 2019). "Nonetheless, a multivariate logistic regression model showed that neither MICA*009 nor the combination MICA*009/HLA-B*51 was associated with melanoma susceptibility." (PMID 25838620, 2015). "Neither mutation nor gene expression change in JAK1, JAK2, B2M, HLA-A, HLA-B, and HLA-C was observed between pre- and post-treatment tumor samples, which were previously indicated to be associated with resistance to PD-1 antibody treatment in melanoma." (PMID 30872362, 2019). "However, a multivariate logistic regression model showed that neither MICA*009 nor the combination MICA*009/HLA-B*51 was associated with melanoma susceptibility." (PMID 25838620, 2015). "However, when a multivariate logistic regression analysis was performed, the results showed that neither MICA*009 nor the combination MICA*009/HLA-B*51 was associated with melanoma susceptibility." (PMID 25838620, 2015). "The effect of both high mean HED (calculated as the mean divergence at HLA-A, HLA-B, and HLA-C) and high TMB on OS after ICB has previously been reported to be more pronounced than the effect of either alone in melanoma." (PMID 34732240, 2021). "Using qRT-PCR to determine the mRNA levels of these four MHC class I molecules in melanoma cells after IR, demonstrated a significant increase of HLA-A and-E mRNA, but not for HLA-B and -C mRNA." (PMID 33789714, 2021). "Cytofluorographic analysis of A375-M6 melanoma cells stained with the HLA-A-specific mAb LGIII-147.4.1, the HLA-B,C-specific mAb B1.23.2 and the HLA-DR,DQ,DP-specific mAb LGII-612.14 demonstrated a high HLA class I antigen expression and a low HLA class II antigen expression." (PMID 31454998, 2019). "The determined HLA restrictions confirmed the predictions of the algorithms and explained the exclusive recognition of Ma-Mel-86a as HLA-A*24:02 and HLA-B*15:01 were not expressed by the other melanoma cell lines." (PMID 28423700, 2017). "Moreover, the rest of SASP-related genes recruited in our risk-scoring model including HLA-B, TPMT, ATM, CD59, TRIM21, and ASPRV1 have not been well studied in melanoma, indicating their potential of novel therapeutic target." (PMID 40864319, 2025). "To prove that the effects we have described were caused by interactions of the HLA-B,C-specific mAb B1.23.2 with the gene products of the HLA-B and C loci and not with unrelated molecules, we tested whether the HLA-B,C-specific mAb B1.23.2 had any effects on the metabolism of FO-1 melanoma cells." (PMID 31454998, 2019). "Similar to anti-CTLA4-treated patient cohort, NLRC5 and HLA-B was reduced in non-responders, along with a similar trend for B2M in anti-PD1-treated melanoma patients." (PMID 33547395, 2021).